NAMPT (nicotinamide phosphoribosyltransferase)
Diseases named in the same sentence as NAMPT in open-access papers (continued):
Sharing a sentence is not in itself a finding about the gene and the disease.
adenoma (1 paper, 2025). A neoplasm arising from the epithelium. "Further analysis revealed that cancer-associated fibroblasts (CAFs) and tumor-associated macrophages (TAMs) in CRC tissues received markedly stronger Nicotinamide phosphoribosyl transferase (NAMPT) signaling compared to normal or adenoma tissues." (PMID 40959269, 2025).
adrenal tumors (1 paper, 2022). "Present studies in adrenal tumors may suggest that visfatin/NAMPT originates from tumors themselves due to no confirmed correlations with the lipid profiles of patients." (PMID 36233428, 2022).
age-related hearing loss (1 paper, 2022). "The NAMPT inhibitor P7C3 leads to otoprotection in an age-related hearing loss model and may emerge in a novel therapeutic strategy for presbycusis." (PMID 35573665, 2022).
alcoholic fatty liver disease (1 paper, 2019). Lipid infiltration of the hepatic parenchymal cells that is due to alcohol abuse. "Our results provide important insights in targeting NAMPT for treating alcoholic fatty liver disease." (PMID 30794635, 2019).
alcoholic liver diseases (1 paper, 2019). A disorder caused by damage to the liver parenchyma due to alcohol consumption. "NAMPT is able to modulate processes involved in the pathogenesis of non-alcohol induced fatty liver disease (NAFLD), but the roles NAMPT plays in development of alcoholic liver disease (ALD) still remain unknown." (PMID 30794635, 2019). "However, whether NAMPT modulates the processes involved in the pathogenesis of alcoholic liver disease (ALD) still remains unknown." (PMID 30794635, 2019).
anaplastic meningioma (1 paper, 2022). A WHO grade III meningioma characterized by the presence of malignant morphologic features, including malignant cytology and a very high mitotic index (20 or more mitoses per ten high power fields). "Then, NAMPT was identified as the critical protein during the tumorigenesis of anaplastic meningiomas." (PMID 35515130, 2022). "The expression of NAMPT was significantly higher in anaplastic meningiomas than in fibrous meningioma tissues." (PMID 35515130, 2022). "First, the study focused on the therapeutic effect of NAMPT inhibitor FK866 on anaplastic meningiomas and immune checkpoints expression." (PMID 35515130, 2022). "The key metabolic enzyme nicotinamide phosphoribosyltransferase (NAMPT) showed upregulated expression in anaplastic meningiomas." (PMID 35515130, 2022). "In conclusion, the expression of NAMPT, which plays a crucial role in energy metabolism, was upregulated in anaplastic meningiomas." (PMID 35515130, 2022). "The expression of NAMPT was significantly higher in the anaplastic meningioma tissues than in the fibrous meningioma tissues." (PMID 35515130, 2022). "To validate the differential expression of NAMPT between fibrous meningiomas and anaplastic meningiomas, we detected the protein level of NAMPT in fibrous meningioma samples (n=6) and anaplastic meningiomas samples (n=3) by Western blot analysis." (PMID 35515130, 2022). "We first validated that NAMPT plays a critical role in the tumorigenesis of anaplastic meningioma and can be a therapeutic target." (PMID 35515130, 2022). "The expression of NAMPT was obviously different between fibrous meningiomas and anaplastic meningiomas." (PMID 35515130, 2022). "Our results demonstrated that NAMPT inhibitors could potentially be an effective treatment method for patients suffering from anaplastic meningiomas." (PMID 35515130, 2022).
angina pectoris (1 paper, 2015). The symptom of paroxysmal pain consequent to MYOCARDIAL ISCHEMIA usually of distinctive character, location and radiation. "There is also a significantly positive correlation between plasma concentrations of NAMPT and high sensitivity C-reactive protein (hs-CRP) and IL-6 in the patients with stable angina pectoris." (PMID 26389889, 2015).
Aortic dissection (1 paper, 2024). Aortic dissection refers to a tear in the intimal layer of the aorta causing a separation between the intima and the medial layers of the aorta. "For example, the reduced content of nicotinamide phosphoribosyltransferase (NAMPT) was observed in patients with dilated aortopathy, and VSMC nampt-deficiency in mice was found to aggravate AngII-induced aortic dissection due to the decrease of the intrinsic NAD+ levels." (PMID 38673941, 2024).
aortic stenosis (1 paper, 2025). Aortic valve stenosis is a aortic valve disease caused by the incomplete opening of the aortic valve. "The aim of this study was to determine whether exosomes from Nicotinamide phosphoribosyltransferase (NAMPT)-overexpressing mesenchymal stem cells (MSC NAMPT-Exo) can attenuate aortic stenosis (AS) and explored the underlying mechanism." (PMID 41516133, 2025).
aortic valve disease (1 paper, 2025). "SisselÅkra and colleagues further examined the expression of the senescencemarker sirtuin 1 (SIRT1) and nicotinamide phosphoribosyltransferas (NAMPT)enzyme, which regulates SIRT1 activity, in EAT, PAT, and SAT from CHD patients,using individuals with aortic valve disease as controls." (PMID 40160564, 2025).
Atrophy (1 paper, 2025). Any weakening or degeneration, especially through lack of use. "NAMPT knockdown diminished the MSC/NAD+‐MSC–dependent decrease in Atrogin 1/MuRF1 levels and the increase in myotube diameter, indicating that NAD+ enhances the therapeutic effect of MSCs on muscle atrophy by promoting NAMPT secretion." (PMID 41383117, 2025).
bacterial sepsis (1 paper, 2025). "The eight differentially expressed genes (DEGs) as key diagnostic markers for bacterial sepsis: FTH1, B2M, NAMPT, KLF6, SRGN, S100A6, S100A9, and S100A8." (PMID 41303672, 2025).
bladder tumor (1 paper, 2023). "Similarly, combining 1MT with the nicotinamide phosphoribosyl transferase (NAMPT) inhibitor, APO866, resulted in a greater effect on both murine gastric and bladder tumor models than either treatment alone." (PMID 36980629, 2023).
breast cyst (1 paper, 2016). A fluid-filled closed cavity or sac that is lined by an EPITHELIUM and found in the BREAST. "In conclusion higher levels of visfatin/NAMPT and TNF-α in the fluid from simple and complex breast cysts than in plasma suggest that their local production is related to inflammation." (PMID 27293305, 2016). "Contrarily, the levels of visfatin/NAMPT and TNF-α were significantly increased, and IL-6 levels were similar in the breast cyst fluid and plasma in both study groups." (PMID 27293305, 2016). "Higher levels of visfatin/NAMPT and TNF-α in the fluid from simple and complex breast cysts than in plasma suggest that their local production is related to inflammation." (PMID 27293305, 2016). "Thus, on the basis of our results and previously published studies we suggest that visfatin/NAMPT concentration in breast cyst fluid but not in the circulation may be a potential marker for stratification of the risk of cancer development." (PMID 27293305, 2016).
Cachexia (1 paper, 2021). Severe weight loss, wasting of muscle, loss of appetite, and general debility related to a chronic disease. "As seen in our investigation, NAMPT expression in the cachexia group was significantly increased with NR administration, whereas SIRT1 levels decreased." (PMID 34262449, 2021).
cervical adenocarcinoma (1 paper, 2024). An adenocarcinoma arising from the cervical epithelium. "In the case of the cervix, NAMPT is highly expressed in cervical adenocarcinoma." (PMID 38999946, 2024).
Chronic colitis (1 paper, 2022). A chronic inflammatory disease of the large intestine (colon, cecum and rectum). "rCT-NAMPT effectively suppressed the severity of disease in DSS-induced acute and chronic colitis models through targeting the colon and inhibiting the interaction of NAMPT with CYBB or TLR4." (PMID 36552583, 2022). "Further, the expression of NAMPT and CYBB markedly increased in association with increased disease severity in normal mice or those with acute or chronic colitis." (PMID 36552583, 2022).
chronic pancreatitis (1 paper, 2019). A chronic inflammatory process causing damage and fibrosis of the pancreatic parenchyma. "While normal pancreatic tissues were generally negative for NAMPT IHC staining, normal pancreatic ductal epithelial cells showed significant (3+) NAMPT IHC staining in the areas of chronic pancreatitis." (PMID 30856230, 2019).
colon adenocarcinoma (1 paper, 2020). "Data obtained from the Cancer Genome Atlas (TCGA) also showed NAMPT mRNA expression levels in colon Adenocarcinoma (COAD) patient tissues were significantly higher than nontumorous tissues." (PMID 32005247, 2020).
congenital neutropenia (1 paper, 2024). "A study using neutrophil precursors from patients with severe congenital neutropenia showed that upon stimulation with G-CSF CN neutrophils upregulate nicotinamide phosphoribosyl transferase (NAMPT)." (PMID 38450755, 2024).
delirium (1 paper, 2023). A disorder characterized by confusion; inattentiveness; disorientation; illusions; hallucinations; agitation; and in some instances autonomic nervous system overactivity. "NAMPT and CD38, two enzymes catalyzing direct steps in the production and consumption of NAD+, are both elevated in CSF prior to surgery in delirium patients." (PMID 37759795, 2023).
dengue (1 paper, 2020). "Several genes, e.g., NAMPT and CACNA1E, which were identified as the potential target genes of miR-320a in silico, were significantly downregulated under the severe dengue conditions." (PMID 32934118, 2020).
dental caries (1 paper, 2023). The decay of a tooth, in which it becomes softened, discolored, and/or porous. "First, the SNP rs73723358 identified as a possible vQTL at the suggestive level in COHRA2 is located near the gene NAMPT that was previously reported to be associated with dental caries in the permanent dentition in a Hispanic/Latino population." (PMID 36981009, 2023). "Though the direct role of NAMPT in dental caries is not clear and rs73723358 does not have a known eQTL or regulatory effects on NAMPT, this SNP interacted with SSB intake influencing caries in the primary dentition in our study." (PMID 36981009, 2023).
endometriosis (1 paper, 2023). The growth of functional endometrial tissue in anatomic sites outside the uterine body. "Thus, we hypothesized that higher resistin levels in endometrioma fluid is similar to visfatin/NAMPT is an indicator of local inflammation in endometriosis." (PMID 38075048, 2023).
endotoxemia (1 paper, 2008). "Moreover, NAMPT inhibition reduced intracellular NAD concentration in inflammatory cells and circulating TNFα levels during endotoxemia in mice." (PMID 18493620, 2008).
follicular thyroid cancers (1 paper, 2015). "Recently, higher NAMPT immunohistochemical expression was found in the nuclear and cytoplasmic compartments in papillary and follicular thyroid cancers as compared with benign lesions." (PMID 25946974, 2015).
gastrointestinal stromal tumor (1 paper, 2021). "Lastly, the single-dose administration (20 mg/kg) of two novel anti-c-KIT antibody–drug conjugates, with novel NAMPT inhibitors as payloads, efficiently blocked in vivo tumor proliferation in c-Kit-positive gastrointestinal stromal tumor GIST-T1 mouse xenografts." (PMID 34068917, 2021).
gout (1 paper, 2026). A condition characterized by painful swelling of the joints, which is caused by deposition of urate crystals. "Experimental validation confirmed these findings: qPCR analysis demonstrated that the mRNA levels of JAK1, CSF1R, and NAMPT were significantly elevated in cellular models simulating both gout and MetS conditions." (PMID 42063773, 2026).
granulosa cell tumor (1 paper, 2023). A slow-growing, malignant tumor, characterize by the presence of granulosa-like cells and Call-Exner bodies, that is almost always found in the ovary. "Similarly, non-cancer ovarian granulosa cells (HGrC1) showed 1.39-fold higher expression of NAMPT mRNA than granulosa cell tumors (KGN cells) (*P < 0.05)." (PMID 36658296, 2023).
gynecologic cancer (1 paper, 2024). "In this section, we will highlight the antitumor effects of NAMPT inhibitors both in vitro and in vivo in gynecologic cancer models, as well as advancements in their clinical applications." (PMID 39272943, 2024). "Besides NAMPT, enzymes in other NAD+ biosynthesis pathways have been considered as potential targets in gynecologic cancer cell lines." (PMID 39272943, 2024).
heart arrhythmia (1 paper, 2019). "Five genes (PRKCG, EREG, BHLHE40, KLF10, and NAMPT) targeted by AA-miRNAs may contribute to the pathogenesis of heart arrhythmia such as AF." (PMID 31607954, 2019).
Hyperammonemia (1 paper, 2023). An increased concentration of ammonia in the blood. "However, experimentally, expression of the critical enzymes NAMPT and NMNAT are both decreased during hyperammonemia and this reduced expression is reversed by restoration of NAD+ concentrations, suggesting their redox dependency." (PMID 37101412, 2023).
hypercoagulability (1 paper, 2025). "In conclusion, JHP ameliorates early NONFH by regulating lipid metabolism, improving hypercoagulability, and restoring bone homeostasis through the NMNAT1/NMNAT3/NAMPT/STK11/HMGCR/ACAT1 axis." (PMID 40988117, 2025).
juvenile idiopathic arthritis (1 paper, 2017). Juvenile idiopathic arthritis (JIA) is the term used to describe a group of inflammatory articular disorders of unknown cause that begin before the age of 16 and last over 6 weeks. "Even beyond the mere clinical association with inflammatory disease such as juvenile idiopathic arthritis, NAMPT was found to inhibit the pharmacological activity of methotrexate and was suggested as a predictive biomarker of response, as well as a potential therapeutic target." (PMID 28837586, 2017).
leiomyosarcoma (1 paper, 2020). An uncommon, aggressive malignant smooth muscle neoplasm, usually occurring in post-menopausal women. "Another study indirectly linked vitamin B3 to uterine tumors, where nicotinamide phosphoribosyltransferase (NAMPT), which catalyzes one of the steps in NAD synthesis, was involved in tumors originating from the myometrium, such as rhabdomyosarcoma (RMS) and leiomyosarcoma (LMS)." (PMID 32752274, 2020).
lung adenocarcinoma (1 paper, 2023). A carcinoma that arises from the lung and is characterized by the presence of malignant glandular epithelial cells. "In addition, the ferroptosis phenotype was reversed by overexpressing NAMPT, which in turn resulted in a significant rescue of the proliferative capacity of lung adenocarcinoma cells, with the additional recovery of the tumor-promoting effects in vivo in the presence of high-dose NMN." (PMID 37173894, 2023).
meningioma (1 paper, 2022). A generally slow growing tumor attached to the dura mater. "In vitro, NAMPT inhibitor -FK866 reduced the viability of anaplastic meningiomas by inducing cell cycle arrest at the G2/M phase." (PMID 35515130, 2022). "In our study, NAMPT inhibitors were used to suppress the growth of anaplastic meningiomas; at the same time, the expression of PD-L1 and B7-H3 was reduced, which means that FK866 can improve the tumor microenvironment and inhibit immune escape." (PMID 35515130, 2022). "The NAMPT inhibitor -FK866 significantly suppressed the growth of anaplastic meningiomas in vitro and in vivo." (PMID 35515130, 2022). "In conclusion, we showed that anaplastic meningiomas have a high level of NAMPT expression, and we inhibited the growth of tumors in vivo and in vitro by applying an NAMPT inhibitor FK866." (PMID 35515130, 2022). "In this study, we assessed whether NAMPT plays a critical role during the tumorigenesis of anaplastic meningiomas and investigated the potential mechanism by which FK866 suppresses the growth of tumors." (PMID 35515130, 2022). "We also aimed to determine whether NAMPT regulates the immune checkpoint in anaplastic meningiomas by regulating STAT1." (PMID 35515130, 2022).
mesenchymal tumors (1 paper, 2018).
metastasis (1 paper, 2021). The spread or migration of cancer cells from one part of the body (where they first appeared) to another. "The expression level of NAMPT is related to the patient’s age, gender (highly expressed in women), tumor stage, tumor lymph node metastasis, and tumor diameter, while the expression level of NAMPT is not statistically related to the patient’s smoking history and tumor metastasis." (PMID 33540574, 2021).
myeloid neoplasm (1 paper, 2025). Proliferation of myeloid cells originating from a primitive stem cell. "Nicotinamide phosphoribosyltransferase (NAMPT), a rate-limiting enzyme in the nicotinamide adenine dinucleotide (NAD) salvage pathway, is a potential target in cancer and of particular interest in myeloid neoplasms due to the location of the NAMPT gene at 7q22.3." (PMID 39997326, 2025).
Myocardial fibrosis (1 paper, 2023). "NAMPT has been reported to be expressed in periadventitial and apical epicardial AT, and this local production has been suggested to play a role in myocardial fibrosis and remodelling and in reverse left ventricular remodelling after aortic valve replacement." (PMID 37730614, 2023).
nonalcoholic fatty liver (1 paper, 2024). "Association between NAMPT gene rs2058539 polymorphism and different variables in 152 patients with biopsy-proven nonalcoholic fatty liver." (PMID 39045924, 2024). "Distribution of the visfatin gene (NAMPT) rs2058539 variant in the cases with biopsy-proven nonalcoholic fatty liver and the controlsa." (PMID 39045924, 2024).
ovarian granulosa cell tumor (1 paper, 2023). A granulosa-stromal cell tumor that arises from the ovary. "However, no study has examined NAMPT expression in ovarian granulosa cell tumors, which are rare but can metastasize aggressively to the peritoneal cavity." (PMID 36658296, 2023).
overnutrition (1 paper, 2022). An imbalanced nutritional status resulting from excessive intake of nutrients. "We next subjected NAMPTfl/fl (WT) and NAMPTLKO mice to 12wk Western diet feeding to test the hypothesis that hepatocyte NAMPT protects against the deleterious metabolic effects of overnutrition." (PMID 35228549, 2022).
Pleural effusion (1 paper, 2021). The presence of an excessive amount of fluid in the pleural cavity. "In this study, we investigated the concentration of NAMPT in pleural effusions of various etiologies." (PMID 34702907, 2021). "Last but not least, blood samples were not collected from patients in our study, so we were unable to compare NAMPT levels in serum and pleural effusions in patients with pleural effusions." (PMID 34702907, 2021). "However, continued studies are needed to further explore the role of NAMPT in pleural effusions." (PMID 34702907, 2021).
pneumococcal infection (1 paper, 2023). Infections with bacteria of the species streptococcus pneumoniae. "We then aimed to confirm the regulation of NAMPT and NMNAT1 upon pneumococcal infection in primary cell culture infection models." (PMID 37783679, 2023).
polycystic ovarian syndrome (1 paper, 2025). "In particular, miR-4799-5p has been recognized as a potential biomarker for polycystic ovarian syndrome and is anticipated to target NAMPT and MAPK1, highlighting its putative involvement in the molecular pathways associated with the condition." (PMID 39897041, 2025).
retinal disease (1 paper, 2018). "Based upon our present experimental observations, future preclinical studies evaluating NMN or other therapies that have a direct impact on NAMPT expression and NAD+ metabolism in the context of aging and age-related retinal disease development and progression are highly warranted." (PMID 29905535, 2018).
rheumatic diseases (1 paper, 2020). "In rheumatic diseases, visfatin/PBEF/NAMPT has been described as primarily a pro-inflammatory peptide." (PMID 33192583, 2020).